PIM1 (Pim-1 proto-oncogene, serine/threonine kinase)
Description:
Proto-oncogene with serine/threonine kinase activity involved in cell survival and cell proliferation and thus providing a selective advantage in tumorigenesis. Exerts its oncogenic activity through: the regulation of MYC transcriptional activity, the regulation of cell cycle progression and by phosphorylation and inhibition of proapoptotic proteins (BAD, MAP3K5, FOXO3). Phosphorylation of MYC leads to an increase of MYC protein stability and thereby an increase of transcriptional activity (By similarity). The stabilization of MYC exerted by PIM1 might explain partly the strong synergism between these two oncogenes in tumorigenesis (By similarity). Mediates survival signaling through phosphorylation of BAD, which induces release of the anti-apoptotic protein Bcl-X(L)/BCL2L1 (By similarity). Phosphorylation of MAP3K5, another proapoptotic protein, by PIM1, significantly decreases MAP3K5 kinase activity and inhibits MAP3K5-mediated phosphorylation of JNK and JNK/p38MAPK subsequently reducing caspase-3 activation and cell apoptosis. Stimulates cell cycle progression at the G1-S and G2-M transitions by phosphorylation of CDC25A and CDC25C. Phosphorylation of CDKN1A, a regulator of cell cycle progression at G1, results in the relocation of CDKN1A to the cytoplasm and enhanced CDKN1A protein stability. Promotes cell cycle progression and tumorigenesis by down-regulating expression of a regulator of cell cycle progression, CDKN1B, at both transcriptional and post-translational levels. Phosphorylation of CDKN1B, induces 14-3-3 proteins binding, nuclear export and proteasome-dependent degradation. May affect the structure or silencing of chromatin by phosphorylating HP1 gamma/CBX3. Also acts as a regulator of homing and migration of bone marrow cells involving functional interaction with the CXCL12-CXCR4 signaling axis (By similarity). Acts as a positive regulator of mTORC1 signaling by mediating phosphorylation and inhibition of DEPDC5 component of the GATOR1 complex. Acts as a negative regulator of innate immunity by mediating phosphorylation and inactivation of GBP1 in absence of infection: phosphorylation of GBP1 induces interaction with 14-3-3 protein sigma (SFN) and retention in the cytosol. Also phosphorylates and activates the ATP-binding cassette transporter ABCG2, allowing resistance to drugs through their excretion from cells. Promotes brown adipocyte differentiation (By similarity).
Synonyms: PIM
Tractability: Small molecule: a drug acting on it is in phase 1 trials; a structure with a bound ligand is known; a high-quality ligand is known; it has a high-quality binding pocket; it belongs to a druggable protein family. Antibody: its Gene Ontology location is reachable by antibodies, with high confidence; UniProt places it where antibodies can reach, with medium confidence. PROTAC: UniProt records ubiquitination sites on it; ubiquitination databases record sites on it; a small molecule that binds it is known.
Target class: Kinase; Protein Kinase; CAMK protein kinase group; Enzyme; CAMK protein kinase PIM family
Chemical probes: IMIDAZOPYRIDAZIN 1, LGH-447 (high quality), MITOXANTRONE, PD083903, PD084394, PD134583, PD134584
Safety:
Unwanted effects reported when the protein is acted on. In parentheses: how it was acted on, where the effect was seen, and who reports it.
heart disease (cardiovascular system; source: Force et al. (2011))
Gene: Protein-coding gene on chromosome 6 (37,170,152 to 37,175,428, forward strand). Ensembl gene ENSG00000137193.
Subcellular location: Cytoplasm (Isoform 1); Nucleus; Cell membrane (Isoform 2)
Subcellular location (Human Protein Atlas): Cytosol; Nucleoli; Nucleoplasm
Pathways (Reactome):
Disease: STAT5 activation downstream of FLT3 ITD mutants; Signaling by FLT3 fusion proteins
Immune System: Interleukin-4 and Interleukin-13 signaling; Regulation of GBP-mediated host defense
Gene Ontology:
Molecular function: ATP binding; manganese ion binding; protein binding; protein serine kinase activity; protein serine/threonine kinase activity; protein kinase activity
Biological process: cellular response to type II interferon; negative regulation of innate immune response; positive regulation of cardiac muscle cell proliferation; positive regulation of cardioblast proliferation; positive regulation of TORC1 signaling; vitamin D receptor signaling pathway; negative regulation of apoptotic process; negative regulation of defense response to bacterium; positive regulation of brown fat cell differentiation; regulation of mitotic cell cycle; positive regulation of DNA-templated transcription; protein stabilization; regulation of hematopoietic stem cell proliferation
Cellular component: cytoplasm; cytosol; nucleolus; nucleoplasm; nucleus; plasma membrane
Genetic constraint (gnomAD): Loss-of-function variants: 9 observed, 35.74 expected, observed/expected ratio (o/e) 0.25, 90% interval 0.15 to 0.44. The upper end of that interval is the gene's LOEUF score, 0.44, which puts it in group 1 of 6, group 1 being the genes least tolerant of losing a copy. Missense variants: 274 observed, 437.33 expected, observed/expected ratio (o/e) 0.63, 90% interval 0.57 to 0.69. Synonymous variants: 199 observed, 188.69 expected, observed/expected ratio (o/e) 1.05, 90% interval 0.94 to 1.19.
Cancer hallmarks: change of cellular energetics (promotes); invasion and metastasis (promotes); escaping programmed cell death (promotes); proliferative signalling (promotes); angiogenesis (promotes)
Homologues: Orthologues: chimpanzee PIM1 (100% identical), macaque PIM1 (100% identical), pig PIM1 (99% identical), rabbit PIM1 (97% identical), rat Pim1 (97% identical), mouse Pim1 (94% identical), guinea pig PIM1 (94% identical), dog PIM1 (92% identical), zebrafish pim1 (72% identical), tropical clawed frog pim1 (64% identical). Paralogues in human: PIM3 (69% identical), PIM2 (54% identical).
Diseases named in the same sentence as PIM1 in open-access papers:
PIM1 is named in the same sentence as 191 diseases in open-access papers, as found by Europe PMC text mining. Sharing a sentence is not in itself a finding about the gene and the disease. The quoted sentences say what the papers report.
prostate carcinoma (88 papers, 2005 to 2025). A carcinoma that arises from epithelial cells of the prostate gland. "PIM1 induction is a well-established mechanism causing chemotherapeutic resistance in different tumors, including prostate cancer." (PMID 38097734, 2024). "Further studies are needed to dissect the precise mechanisms underlying TG accumulation and utilization following PIM1 induction in prostate cancer." (PMID 38097734, 2024). "While PIM1 is implicated as an important factor mediating prostate cancer growth and resistance to therapy, few studies have investigated a potential role for PIM in LD accumulation." (PMID 38097734, 2024). "We then questioned if PTEN or androgen receptor (AR) status can affect LD accumulation associated with PIM1 in prostate cancer." (PMID 38097734, 2024). "Collectively, these data indicate that activation of PPARα downstream of PIM1 is essential for LD accumulation and underscore the role of LD accumulation in mediating PIM1-associated cell proliferation in prostate cancer." (PMID 38097734, 2024). "We first focused on candidates, which strongly adhered to the PIM1 consensus motif, had high peptide counts, and had been previously linked to human prostate cancer." (PMID 33398037, 2021). "Spearman correlation analysis revealed that NDRG1 pS330 levels in prostate cancer are associated with AR pS213 (r = 0.3664, p = 0.01) and PIM1 protein levels (r = 0.5038, p = 0.00003)." (PMID 33398037, 2021). "PIM1 has also been linked to a variety of oncogenic processes in both prostate cancer and other cancers, including cell-cycle progression, genomic instability, resistance to chemotherapeutics, and increased tumorigenicity in mouse xenograft models." (PMID 34697370, 2021). "For example, deprivation of Dicer-derived mir-124 and mir-144 by hypoxia contributes to the loss of inhibition of PIM1, a well-recognized oncogene of prostate cancer and subsequent activation of autophagy in prostate cancer cells (DU145 and PC3 cells)." (PMID 32774363, 2020). "Abnormal expression of PIM1 has been linked to hematological malignancies, colon, bladder, head and neck squamous cell carcinoma, and prostate cancer, including the neuroendocrine variant: one of its most aggressive forms." (PMID 32504181, 2020). "The PIM1 oncogene has been implicated in various human cancers including lymphomas, gastric, colorectal, and prostate carcinomas." (PMID 29467592, 2018). "PIM1 was found to be overexpressed in gastric and prostate cancers, which was associated with aggressive clinicopathological features." (PMID 25834102, 2015). "PIM1: It encodes a protein kinase which was also found to be upregulated in prostate cancer by CDNA microarrays." (PMID 24282788, 2013). "PIM-1 and PIM-2 are implicated in prostate cancer development, PIM-1 is over expressed in head and neck squamous cell carcinoma and bladder cancer and PIM-3 is over expressed in colorectal, pancreatic and hepatocellular carcinoma." (PMID 22193779, 2011). "PIM1 is an oncogene whose over-expression has been associated to the acquisition of drug resistance in prostate cancer." (PMID 22140532, 2011). "PIM1 has been implicated as an oncogene whose expression is dysregulated in several human cancers including lymphomas, gastric, colorectal and prostate cancers." (PMID 20515470, 2010). "The serine/threonine kinase PIM1 has been implicated as an oncogene in various human cancers including lymphomas, gastric, colorectal and prostate carcinomas." (PMID 20515470, 2010). "Pim1 encodes a serine/threonine kinase that is frequently overexpressed in human prostate cancer, while Mycn encodes a transcription factor related to Myc that is amplified in a variety of human tumours, most notably neuroblastomas." (PMID 19285540, 2009).
prostate carcinoma (continued). "Finally, targeting PIM1 or PPARα signaling was sufficient to abrogate the proliferative and survival functions associated with LD accumulation or PIM1 in prostate cancer." (PMID 38097734, 2024). "Moreover, targeting PIM1 or PPARα signaling using genetic or chemical means abrogates the proliferative and survival advantage associated with LD accumulation and PIM1 induction in prostate cancer." (PMID 38097734, 2024). "We believe that these TG species, especially TG(15:0/14:0/15:0), which showed approximately 10 log2FC increase, could be critical for PIM1-associated regulation of LD accumulation in prostate cancer." (PMID 38097734, 2024). "PIM1 was also showed to promote highly aggressive, neuroendocrine variant of prostate cancer by epigenetic changes in H19, suggesting it may be implicated in malignant neuroendocrine transformation." (PMID 32504181, 2020). "Maybe most interestingly in regard to our data on promotion of prostate cancer cell motility by PIM1 and NFATC1, there were several genes encoding regulators of the cytoskeletal actin network (INF2, FHOD1, ACTN3, CORO1B) and cell adhesion (COL6A2, PXN, ITGA5)." (PMID 31730483, 2019). "The Hi-Myc mouse model expresses human c-MYC in the prostate and recapitulates human prostate cancer on a genetic level, since cancers harbor loss of the tumor suppressor Nkx3.1 and upregulation of the serine/threonine kinase Pim-1, which are also prevalent in human prostate cancer." (PMID 29212195, 2017). "Various investigations have linked Pim-1 to aggressive malignant behavior and poor clinical outcome in many cancer cells, including gastric cancer, prostate cancer, esophageal squamous cell carcinoma, breast cancer, lung cancer, colon cancer, and hematological cancer." (PMID 25551195, 2014). "Pim1 has been implicated in prostate cancer as a prognostic factor." (PMID 23565217, 2013). "A significant association between ERG and PIM1 expression in clinical prostate carcinoma specimens was found, suggesting that such a mechanism may be relevant in vivo." (PMID 22140532, 2011). "Because we observed that inhibiting Pim1 diminishes osteoclast activity, we asked whether treating a mouse model of prostate cancer cell-associated osteolysis with SGI-1776 can reduce both the prostate cancer-cell proliferation and the osteolytic activity of osteoclasts." (PMID 40164682, 2025). "PIM1 is a serine/threonine kinase known to act as an oncogene in multiple cancers, such as leukemia, myeloma, breast and prostate cancers, by phosphorylating target proteins involved in apoptosis, cell cycle progression, migration, and metabolism." (PMID 40992658, 2025). "The proto-oncogene, serine/threonine kinase (PIM1) belongs to the Ser/Thr protein kinase family and is overexpressed in hematopoietic malignancies and in prostate cancers." (PMID 40649898, 2025). "Previous studies have reported that Pim1 facilitates the progression of prostate cancer by promoting the migration, proliferation and survival of the cancer cells." (PMID 40164682, 2025). "To evaluate differences in the extent of prostate cancer-induced osteolysis between WT and Pim1−/− mice, we injected RM1 cells into both groups." (PMID 40164682, 2025). "It was shown that PIM1 phosphorylated N-myc downstream–regulated gene 1 to mediate prostate cancer cell invasion and metastasis." (PMID 40992658, 2025). "PIM1 is an established oncogene, though this is generally because of observed elevation of expression, for instance in prostate cancer." (PMID 41152984, 2025). "A possible explanation for this observation is that PIM1 overexpressing prostate cancer cells can effectively deliver fatty acids from the LDs to peroxisomes and mitochondria for energy production to promote survival during nutrient stress." (PMID 38097734, 2024). "Here we identify PIM1 as a driver of LD accumulation and demonstrate a critical role for this event for prostate cancer cell proliferation and survival during nutrient stress." (PMID 38097734, 2024).
prostate carcinoma (continued). "Collectively, this data highlights the involvement of PIM1 in altering lipid composition in prostate cancer." (PMID 38097734, 2024). "Taken together, the data show that PIM1 promotes survival during nutrient stress through LD fatty acid utilization in prostate cancer." (PMID 38097734, 2024). "Here, we identify PIM1 as a driver of LD accumulation and show a significant effect of PIM1 expression on prostate cancer proliferation and survival, particularly during nutrient stress." (PMID 38097734, 2024). "We observed that PIM1 induction increased the production of specific TG species that are known to facilitate LD accumulation in prostate cancer cells." (PMID 38097734, 2024). "To test this, we utilized a prostate cancer cell line (PC3TripzPIM1) stably expressing a doxycycline-inducible PIM1 vector (TripzPIM1)." (PMID 38097734, 2024). "The contribution of other phospholipid classes associated with PIM1 upregulation toward LD monolayer is minimal and usually context-dependent; nonetheless, it is conceivable these changes might have direct or indirect implications in prostate cancer progression." (PMID 38097734, 2024). "In prostate cancer, PIM-1 activation is particularly significant, contributing to tumor progression and aggressiveness, especially in castration-resistant prostate cancer (CRPC)." (PMID 39434908, 2024). "The impact of PIM-1 in prostate cancer underscores its importance in oncology and the ongoing efforts to develop targeted therapies against it." (PMID 39434908, 2024). "Overexpression of PIM1 increases LD number and size in both in vitro and in vivo models of prostate cancer." (PMID 38097734, 2024). "Collectively, the results indicate that PIM1 regulates LD accumulation in prostate cancer by inhibitory phosphorylation of GSK3β at S9." (PMID 38097734, 2024). "Second, the induction of antiapoptotic signals by BMX are observed in different cancer types, including BCL2/BCL-xl expression in SCLC, and PIM-1 expression in prostate cancer." (PMID 39133652, 2024). "Based on these findings, we proposed a model whereby PIM1 drives LD accumulation by phosphorylating and inhibiting GSK3β in prostate cancer." (PMID 38097734, 2024). "The accumulation of LDs downstream of PIM1 enhances prostate cancer survival during nutrient stress." (PMID 38097734, 2024). "Taken together, these data indicate that PIM1 amplifies peroxisomal biogenesis by inhibiting GSK3β-PPARα signaling to induce LD accumulation in prostate cancer." (PMID 38097734, 2024). "First, we examined PPARα stability using a cycloheximide chase assay in DU145 prostate cancer cells stably expressing vector (DU145pCIP) or PIM1 (DU145hPIM1)." (PMID 38097734, 2024). "In the vehicle-treated mice, control tumors grew more rapidly than shUSP28 tumors, indicating that USP28 promotes tumor growth in this prostate cancer model, potentially by inducing PIM1/2 expression." (PMID 35326457, 2022). "Quercetagetin was shown to inhibit PIM1 activity in prostate cancer cells and to have antiproliferative activity in cervical, breast, and lung cancer cell lines in a dose-dependent manner." (PMID 36243702, 2022). "In the treatment of prostate cancer, myricetin promotes prostate cancer cell apoptosis and antimetastatic effects by inhibiting PIM1 and by disrupting its interaction with CXCR4." (PMID 36091790, 2022). "Studies in prostate cancer found PIM1 affected stem cell proliferation, self-renewal, and expansion." (PMID 35892829, 2022). "PIM1-mediated AR serine 213 phosphorylation (pS213) differentially impacts AR target gene expression and is correlated with prostate cancer recurrence." (PMID 33398037, 2021). "Here, we sought to characterize how PIM1 phosphorylation of AR and the AR co-activator, 14-3-3 ζ, alters AR transcriptional activity in prostate cancer." (PMID 34697370, 2021). "Through our studies, we have further characterized the mechanism by which PIM1 phosphorylation of AR alters AR transcriptional activity in prostate cancer." (PMID 34697370, 2021).